IL6 (interleukin 6)
Diseases named in the same sentence as IL6 in open-access papers (continued):
Sharing a sentence is not in itself a finding about the gene and the disease.
ovarian tumor (continued). "Taken together, the results demonstrate that pHLIP-PNA3-mediated HOTAIR inhibition reduces ovarian tumor levels of IL-6, MMP-9, and ALDH1A1, increases CDDP sensitivity and improves overall survival." (PMID 28420874, 2017). "The production of acute-phase proteins is generated by different stimuli involving cytokines (TNF, IL-1, and IL-6), which are secreted by ovarian tumor cells in vitro and in vivo." (PMID 25183900, 2014). "A recent study has demonstrated metastatic and drug-resistant recurrent ovarian tumors to have a significantly higher IL-6 expression compared to the matched primary tumors." (PMID 24782986, 2014). "IL-6 expression in the ovarian tumor microenvironment can impact host immune defense mechanisms as well as tumor cell growth, proliferation, differentiation and angiogenesis." (PMID 23593315, 2013). "With respect to mechanism, PDAC cell lines and ovarian tumour cells treated with conditioned medium from CAFs were shown to have increased resistance to paclitaxel, attributed to the presence of IL-6 secreted by the CAFs which has been found to promote survival in tumour cells." (PMID 34865180, 2023). "In human breast and ovarian tumors, it has been shown that CAFs could facilitate the stroma inflammation by expressing high levels of IL-6, COX-2 and CXCL1." (PMID 33771156, 2021). "In addition, the concentration of IL-6 increases after platinum treatment of ovarian tumours, and IL-6 secreted by stromal fibroblasts activates STAT3 and enriches the numbers of ALDH+ CSCs in residual tumours." (PMID 33023532, 2020). "The use of IL6 may improve preoperative discrimination of suspected ovarian tumours, however the findings in this study alone are insufficient to support it for generalized ovarian screening." (PMID 32042020, 2020). "Furthermore, it has recently been shown that tumor-derived S100A9 induced the production of IL-6 by myeloid cells in ovarian tumors, and that IL-6 drives angiogenesis with defective pericyte coverage typical for TME." (PMID 26673090, 2015). "M-CSF, known as a colony stimulating factor 1 (CSF-1), is also a potent chemoattractant for monocytes, which in turn, can produce factors that stimulate proliferation of ovarian tumor cells including interleukin-1 (IL-1), interleukin-6 (IL-6) and tumor necrosis factor (TNF)." (PMID 25935153, 2015). "To simulate what happens in ovarian tumors, we used IL-1β (10 ng/ml) to induce IL-6 expression in ovarian cancer cells and then examined whether minocycline can block the surge in IL-6 expression." (PMID 23593315, 2013). "Similar to our results, Coffelt and colleagues reported that ovarian tumor-derived leucine, leucine-37 recruits MSCs to the tumor microenvironment and stimulated MSCs secreted larger amounts of pro-angiogenic factors including IL-1 receptor antagonist, IL-6, IL-10 and VEGF to support angiogenesis." (PMID 23763837, 2013). "In conclusion, our studies show that NCX4040 treatment of ovarian tumor cells results in the differential induction of oxidative stress genes, inflammatory response genes (TNF, IL-1, IL-6 and COX2), DNA damage response and MAP kinase response genes." (PMID 36612280, 2022). "In this study, we provide evidence that NCX4040 induces the differential induction of oxidative stress genes, inflammatory response genes (TNF, IL-1, IL-6 and COX2), DNA damage response and MAP kinase response genes in human ovarian tumor cells." (PMID 36612280, 2022). "It is well-known that pro-inflammatory cytokines, particularly IL-1β, IL-6 or TNF-α, promote ovarian tumor growth and metastasis, and their high serum levels are correlated with poor clinical outcomes." (PMID 34771587, 2021). "In EOC patients, higher M2 TAM accumulation positively correlates with shorter survival rate and STAT3 activators IL-6 and LIF have been shown to drive M2 TAM phenotype switch in ovarian tumors." (PMID 33335857, 2020).
ovarian tumor (continued). "At the same time, ovarian CAFs have been shown to be a major source of IL-6 in the TME, which activates STAT3 in ovarian tumor cells leading to cell proliferation and invasion." (PMID 33335857, 2020). "In ovarian tumor-bearing mice, blood IL-6 levels increased (P < 0.01) after treatment with CDDP alone or pHLIP-control PNA + CDDP, and IL-6 blood levels were reduced (P < 0.05) after pHLIP-PNA3 + CDDP treatment compared to pHLIP-PNA control + CDDP." (PMID 28420874, 2017). "Circulating blood concentrations and expression of SAA, IL6 and IL8 have been shown to be correlated with ovarian tumour stage and also with patient survival." (PMID 22410202, 2012). "Norepinephrine‐mediated activation of ADRB2 signaling could stimulate IL‐6 expression in ovarian tumors, suggesting the potential of sympathetic nerves in regulating the tumor immune microenvironment through the ADRB2/IL‐6 signaling axis." (PMID 41556039, 2026). "Inordinately elevated IL-6 may drive, via the IL6/IER3 signaling axis, chemoresistance and disease recurrence of ovarian tumors; higher levels of IL-6 and VEGA-A were significantly associated with shorter progression-free survival." (PMID 40507922, 2025). "Interestingly, specific inhibition of IL-6, instead of TNF, downregulates the population of TNFR2+ Tregs in advanced ovarian tumor ascites, which indicates that IL-6 is involved in the accumulation of TNFR2+ Tregs." (PMID 35494080, 2022). "Similarly, metformin also showed reduction in IL-6, MCP-1 and VEGF levels, important factors shown to promote ovarian tumor progression." (PMID 25895126, 2015). "In ovarian tumors, functional activity for TLR4 was demonstrated by stimulation of cell lines with specific ligands and subsequent activation and translocation of NF-κB and release of the proinflammatory cytokines interleukin-6 and CCL-2." (PMID 22985132, 2012). "Therefore, we speculated here, that the increased levels of the pro-inflammatory cytokines, IL-1β, IL-6 and TNF-α in tumor-bearing mice is dependent on the production of TNF-α by ovarian tumor cells." (PMID 37305383, 2023).
adenoma (49 papers, 2008 to 2025). A neoplasm arising from the epithelium. "A 4-year nutritional intervention trial featuring a low-fat, high-fiber, high-fruit, and high-vegetable diet found that the intake of flavonoids, such as isoquercitrin, kaempferol, and quercetin, was associated with decreased serum levels of IL-6 and a lower recurrence rate of high-risk adenomas." (PMID 40949141, 2025). "Interestingly, IL-6 was observed to be significantly elevated in patients with colorectal adenoma, and a decrease in IL-6 was negatively associated with high-risk and advanced adenoma recurrence in a previous study." (PMID 37194025, 2023). "Furthermore, loss of Mir34a in adenomas was associated with the induction of RNAs commonly up-regulated after IL6 treatment, which includes STAT3 activation." (PMID 36147476, 2022). "However, the mRNA levels of tumor-associated genes, including Vegf-a, interleukin 6 (Il6), and tumor necrosis factor α (Tnfα), were comparable in all adenomas from Apcmin/+; Crhr1−/−, Apcmin/+; Crhr1+/−, and Apcmin/+; Crhr1+/+ mice." (PMID 33494263, 2021). "Moreover, granulocytes (GR1+), macrophages (Mac1+) and MDSCs (CD11b+/GR1+) in association with a high level of IL6 expression were also significantly (P < 0.05) more represented in Mutyh−/− adenomas." (PMID 26109431, 2015). "In addition, recent data suggest that individuals with chronic, low levels of inflammation (such as increased circulating IL-6 and TNFα) have increased odds of having adenoma and thus increased CRC risk." (PMID 20500855, 2010). "Previously, we reported that high flavonol intake (>30 mg per day) may decrease serum IL-6 and the incidence of high-risk and advanced adenoma recurrence in the PPT." (PMID 20924374, 2010). "Previously, we reported that serum concentrations of IL-6 may be a potential risk indicator for advanced and high-risk adenoma recurrence; furthermore, dietary flavonols decrease elevated IL-6 concentrations and decrease the risk of advanced and high-risk adenoma recurrence." (PMID 20924374, 2010). "A decline in IL-6 expression was observed from proximal colonic adenomas to adenomas located in the left-sided colon and/or rectum." (PMID 40149674, 2025). "Decrease/loss of ADH1B in MFs during the adenoma-carcinoma sequence contributes to disruption of the retinol-mediated suppression of tumor-promoting inflammation in CRC and to the increase of IL-6 in neoplastic tissue." (PMID 37185128, 2023). "In human CRCs, the Mir34aΔIEC adenoma gene signature was associated with EMT, inflammation and actin cytoskeleton signatures, as well as with the TNFα/NFKB, IL6/STAT3 and MAPK signaling pathways." (PMID 36147476, 2022). "IL-6 is an inflammatory cytokine produced by several types of cells e.g., T lymphocytes, macrophages, adenoma/CRC cells, and surrounding stromal cells." (PMID 36466926, 2022). "Accordingly, in IL-6/sIL-6R double transgenic mice, permanent hepatocyte proliferation and formation of adenomas was observed, indicating a possible role of IL-6 trans-signaling for hepatocellular neoplasia." (PMID 31694340, 2019). "Our results establish that IL-6 contributes to maintain senescence by its autocrine action, providing a natural model of IL-6 mediated benign adenoma senescence." (PMID 27902467, 2017). "We analyzed the associations of circulating levels and single nucleotide polymorphisms (SNPs) of IL-6 and TNF-α with risk of colon adenomas in a colonoscopy -based case-control study of 401 incident adenoma cases and 1,050 controls." (PMID 24235998, 2013). "We have previously shown that elevated levels of plasma IL-6 and TNF-α are associated with increased risk of adenomas." (PMID 23442743, 2013). "In fact in healthy subjects, the sIL-2R in men and sIL-6R in women were principally related to IFNγ, which plays an important role in the development of Th1 cells; in adenoma the TNFα in men and IL-4 in women were, respectively, related to IFNγ and IL-6." (PMID 22235223, 2011).
adenoma (continued). "Even if the results of the adenoma study should be handled with prudence considering the number of patients, IFNγ and IL-6 pathways partially regulate Th1 and Th2 cell network homeostasis (IFNγ in men and IL-6 in women, resp)." (PMID 22235223, 2011). "Gender-specific IFNγ (men) and IL-6 (women) pathways still partially regulate Th1 and Th2 cell network homeostasis in adenoma patients, in contrast to colorectal patients." (PMID 22235223, 2011). "In the adenoma group, on the other hand, IFNγ and IL-6 pathways still partially regulated gender specific Th1 and Th2 cell network homeostasis but in neither sex was a significant relationship observed between IL-10 and other Th1/Th2 network components." (PMID 22235223, 2011). "Consistent with results from our prior reports for the study population, subjects with adenomas were older, more likely to be male, had higher waist-hip ratios and increased plasma IL-6." (PMID 20500855, 2010). "The rise of IL-6 levels was even higher in advanced adenomas than in invasive carcinomas." (PMID 40149674, 2025). "Additionally, increased Il-6 gene expression was found in the macroscopically normal colonic regions of mice with adenomas." (PMID 37373142, 2023). "The correlation between the expression of a tissue marker of autophagy, the presence of adenomas and the serum levels of IL-6 can therefore be a starting point in the search for new diagnostic tools for the early diagnosis of CRC, to improve management and patient outcomes with CRC." (PMID 35563601, 2022). "Moreover in a multiple regression model, the only variables that were independently related to the expression of the autophagic protein were the presence of adenomas at colonoscopy and the serum levels of IL-6." (PMID 35563601, 2022). "YYFZBJS decreased expression levels of Foxp3, IL-6 and IL-10 in conventional T cells in adenomas." (PMID 32677955, 2020). "Also, higher levels of pro-inflammatory cytokines, such as tumor necrosis factor-alpha (TNF-α) and interleukin-6 (IL-6), have been observed within adenoma tissues as an expression of an inflammatory state." (PMID 33182693, 2020). "Our findings establish that IL-6 contributes to maintain senescence by its autocrine action, providing a natural model of IL-6 mediated tumor senescence, which may contribute to explain the benign behavior of these abundant adenomas." (PMID 27902467, 2017). "Adenomas from Mutyh−/− mice had a greater infiltrate of Foxp3+ T regulatory cells, granulocytes, macrophages, MDSCs and strong expression of TGF-β-latency-associated peptide and IL6." (PMID 26109431, 2015). "Further confirmation also came from the finding that in adenoma patients, gender-specific pathways IFNγ and IL-6 still partially regulate immune response homeostasis in men and women and in neither sex was a significant relationship observed between IL-10 and the other Th1/Th2 network components." (PMID 22235223, 2011). "As SOCS3 has been shown to inhibit the actions of IL-6 and TNFα in the intestine, we hypothesized that decreased SOCS3 expression in normal mucosa may predispose to adenomas and thus increase risk for CRC." (PMID 20500855, 2010). "Enhanced expression of Pla2g4a was detected in the adenomas of ApcMin/+ mice (an animal model of FAP) vs. normal mucosa of WT mice, accompanied by the overexpression of the inflammatory cytokine IL-6." (PMID 37173923, 2023). "Presence of adenomas correlated with cholesterol (total and LDL) levels, IL-6 levels, and MAPLC3 tissue expression, especially in the right colon." (PMID 35563601, 2022). "From the adenoma stage to the CRC stage, tumor-promoting relevant cytokines, such as IL-6, IL-8, IL-17A and IL-33, are significantly increased." (PMID 36466926, 2022). "In the present study, DMH control animals showed initiation of ACF, promotion into adenoma, and the significant increase in inflammatory mediator (TNF-α and IL-6) levels." (PMID 24995310, 2014).
adenoma (continued). "The exact pathway of interleukin-6 (IL-6), a multifunctional cytokine expressed in CR adenomas, has not yet been discovered." (PMID 40149674, 2025). "Moreover, a correlation between IL1a and IL6 and VEGF expressed in 59 cultured adenoma cells was also found." (PMID 37958702, 2023). "Also, IL-6 knockout mice treated with AOM/DSS formed fewer tumors and smaller adenomas and tumors, suggesting that IL-6 is important to the formation and growth of tumors in CAC." (PMID 35865942, 2022). "Of note, mutations in the interleukin 6 (IL6) signal transducer gp130, which blocked SHP2–Ras–ERK signaling (gp130757F mice), showed reduced Tff1 levels and a phenotype (antropyloric adenomas, but no carcinomas) highly similar to Tff1KO mice." (PMID 32630599, 2020). "Furthermore, wogonoside dramatically decreased the secretion and expression of IL-1β, IL-6 and TNF-α as well as the nuclear expression of NF-κB in adenomas and surrounding tissues." (PMID 27102438, 2016). "Analyses of the proinflammatory cytokines TNF-α, IL-6, and IL-1β in the serum of participants with colorectal adenomas compared to non-adenoma controls revealed that the presence of adenomas do not lead to systemic elevation in the levels of these cytokines." (PMID 25884547, 2015). "In these studies, high levels of flavonol consumption correlated with decreased serum IL-6 levels and reduced adenoma recurrence; however, overall cytokine profiles were not accurate predictors of flavonol consumption or adenoma incidence." (PMID 25884547, 2015). "Additionally, C-X-C Motif Chemokine Ligand 9 (CXCL9) was included based on high nCounter counts in a small adenoma sample set (data not shown), and IL6 was included based on literature studies." (PMID 38979413, 2024). "We assessed the association between plasma endotoxin concentrations, plasma cytokines IL-4, IL-6, IL-8, IL-10, TNF-α, and interferon-γ (IFN-γ) levels, and local cytokine mRNA expression levels of IL-4, IL-6, IL-8, IL-10, IL-17, TNF-α, and IFN-γ in relation to adenomas." (PMID 23442743, 2013). "Specifically, we assessed mRNA expression of mucosal inflammatory cytokines IL-6, IL-10, IL-12, IL-17 and TNF-α in normal rectal biopsies and correlated their expression levels with abundance of Fusobacterium species in adenoma and non-adenoma subjects." (PMID 23335968, 2013).